CD44 (CD44 molecule (IN blood group))
Diseases named in the same sentence as CD44 in open-access papers (continued):
Sharing a sentence is not in itself a finding about the gene and the disease.
cancer (continued). "Cancer stem cells from NSCLC lines (A549 and H2170) were isolated based on expression of surface markers CD166, CD44, and EpCAM." (PMID 29868483, 2018). "Therefore, CD44 may provide a protection mechanism for cancer cells from apoptosis." (PMID 29747682, 2018). "Our results also revealed that A2780-M cells express increased levels of cancer stem cell surface markers such as β-catenin, CD34, CD133, and CD44." (PMID 30046596, 2018). "Hundreds of FOXP3 target genes have been identified in both Treg cells and cancer cells so far, including HER2/ERBB2, SKP2, CD44, BRCA1, p21, and LATS2." (PMID 30011797, 2018). "CUR can prevent cancer by elevating biomarkers, such as CD133, CD44, CD166, and ALDH1, which affect the morphology of cancer cells." (PMID 34466417, 2018). "LncRNA HOTAIR is a strong activator for expression of OCT4, RNF51, CD44, and CD133 genes—all these proteins are involved in reprogramming the gene network to acquire cancer stem cell properties." (PMID 29967761, 2018). "The main ligand for CD44 is hyaluronic acid (HA), an abundant component of the extracellular matrix (ECM) that is expressed by stromal and cancer cells." (PMID 29747682, 2018). "For instance, OPN, upon binding to αvβ3, can activate Rho GTPase via RANKL, subsequently upregulating the expression of CD44 and MMP-9 and resulting in the increased ability for cancer cell movement and metastasis." (PMID 29500465, 2018). "Microarray analysis revealed that DLEU1 knockdown significantly affects expression of a number of cancer-related genes in OSCC cells, including HAS3, CD44, and TP63, suggesting that DLEU1 regulates HA-CD44 signaling." (PMID 30069008, 2018). "We analyzed control and ADH1B overexpressing cells with qRT-PCR for the expression of such genes and found that ADH1B overexpression increases CD44 and CD47 expression in the cancer cells (p < 0.001 and p < 0.001)." (PMID 29861857, 2018). "The commonly reported specific surface markers, such as CD44, CD133, OCT-4, Bmi-1, ALDH1, ABCG2 and KLF4, with high expressions, are usually used to isolate cancer stem cells from cell lines." (PMID 29559853, 2018). "Secondly, FOXP3 represses several key target genes in cancer development, such as BRCA1, CD44, HER2/ERBB2, and SKP2, providing a strong link between FOXP3 and DNA repair system, as well as FOXP3 and cell cycle regulation." (PMID 30011797, 2018). "Several studies have reported the aberrant expression of multiple antigens by cancer stem cells in AML, including CLL-1, CD47, CD44, and ALDH." (PMID 29799854, 2018). "Different cancer stem cell populations were analyzed by flow cytometry using putative surface cancer stem cell markers (CD24, CD44 etc.).Metabolic phenotype varied between different grades of OSCC." (PMID 29460395, 2018). "Similar to other cancer cells, HNSCC CSCs express surface markers such as CD44 and CD133, which are used for identification." (PMID 29515788, 2018). "ALDH activity was recorded mainly in CD44+ cells, showing that ALDH+ cells represented a subpopulation within the CD44+ subpopulation of cancer cells." (PMID 30380687, 2018). "Two top-ranked genes identified by the method, CD44 (1st) and LPP (2nd), are known to promote cancer cell dissemination and metastasis growth after genomic alteration." (PMID 30459309, 2018). "NF‐κB signalling plays a crucial role in cancer stem cell biology 42, and TNF‐α‐induced NF‐κB activation elevated CD44 expression in SCCHN cells, but TRAF6 knockdown markedly attenuated this process." (PMID 29193723, 2018). "These cancer stem cell markers, including CD24, CD44, CD117, CD133, ALDH, ABCG2, OCT4, and Nanog, were significantly higher in Hep3B sphere cells shown by qRT–PCR analysis." (PMID 29848298, 2018). "The number of cells expressing pan-CD44, CD44v9, CD133, and CD24, all of which were reported to be markers of cancer stem-like cells in CRC, increased after disruption of C45 CTOSs." (PMID 29662620, 2018).
cancer (continued). "Furthermore, unlike GS, CD44-KD in the cancer cells did not cause a decrease in HT." (PMID 29674746, 2018). "CD44 has been defined as a potent cancer stem marker in diagnosis of NSCLC, because the xenograft initiation capacity of CD44+-NSCLC cells is much greater than in CD44−-NSCLC cells." (PMID 29691367, 2018). "Cancer cells that undergo an epithelial to mesenchymal transition (EMT) acquire stem cell-like properties and show an increase in CD44 expression." (PMID 29747682, 2018). "Since INK128 was effective in CD44 positive and sorafenib resistant cell lines, we explored the possibility of combining INK128 and sorafenib to achieve greater anti-cancer effects." (PMID 29899840, 2018). "Stem cell markers CD133, CD44, ABCG2, Oct4, Lgr5, and CD24 are also highly expressed in cancer stem cells." (PMID 29422082, 2018). "Recently, vitamin D compounds have also been shown to inhibit cancer stem cells by down regulating cancer stem cell markers (like OCT4, CD44, and LAMA5) and by inhibiting Notch signaling molecules (involved in cancer stem cell maintenance)." (PMID 29849001, 2018). "FSD13 had a greater ability than wild-type IL-2 in stimulating CD4+ T, CD8+ T, and NK cell proliferation, enhancing the expression of CD69, CD183, CD44, and CD54 in these cells, and triggering cancer cell apoptosis." (PMID 30250191, 2018). "qRT-PCR performed to validate the microarray results showed that expression of a number of cancer-related genes, including HAS3, CD44, TP63, and SMYD2, was decreased by siRNAs targeting DLEU1, while expression of CDH1 was increased by DLEU1 knockdown." (PMID 30069008, 2018). "The differential or concurrent expression of CD44 and CD24 markers has been used for identification of cancer stem cells (CSCs) in a variety of human epithelial and sarcomatoid renal cell carcinoma malignancies." (PMID 30648121, 2018). "CD44 and CD133 have been identified as surface biomarkers for cancer cells resistant to chemotherapeutic drugs." (PMID 27244887, 2017). "In comparison, MMP9 localized on the surface of cancer cells can also activate latent TGF-β, albeit in a CD44-dependent manner.CD44 provides a cell surface docking receptor for proteolytically-activeMMP9, resulting in TGF-β-induced myofibroblasts formation." (PMID 28067804, 2017). "Both CD44 (Indian Blood Group molecule) and cyclin-D1 are critical for GBM cancer cell biology and lie upstream or downstream of the PI3K pathway." (PMID 28556811, 2017). "As cancer cells undergo EMT, they lose expression of epithelial differentiation markers and gain expression of genes such as CD44, which is a key marker for CSCs." (PMID 29383121, 2017). "siRNA-mediated knockdown of EXT1 in MCF7/ADR cells significantly reduced cancer stem cell markers, populations of ALDH+and CD44+/CD24- cells, mRNA and protein expression for CD44, and mammosphere number." (PMID 29050299, 2017). "We screened for cancer cells expressing at least one EMT marker, such as ACTA2, EPCAM, CD44, THY1, VIM, FN1, ZEB1 or CDH1." (PMID 29079795, 2017). "A minority of cancer cell population, called cancer stem cells (CSC), with CD44(+/high)CD24(−/low) signature, has been identified in a large variety of cancers." (PMID 28165047, 2017). "Patient-derived aspirates were cultured under sphere forming conditions and isolated primary cultures were further sorted for cancer stem cell subpopulations ALDH1+ and CD44+CD24-/low." (PMID 28423035, 2017). "HA interactions with the CD44 and CD168 (aka., the RHAMM) receptors further promote growth, invasion and treatment resistance in GBM and many other cancers." (PMID 28883992, 2017). "We next examined the real-time PCR results of the expression of the cancer stem cell markers CD133 and CD44 in these cells." (PMID 29069721, 2017). "CD44-positive and CD24-positive cells have been proposed as predictors of prognosis and treatment response in BC, with clinical implications for cancer treatment because of their role in chemoresistance." (PMID 28399903, 2017).
cancer (continued). "5-day induction of TGF-beta significantly elevated CD44+ (positive) and CD117+ (positive) population in SKOV-3 cancer cells." (PMID 29340100, 2017). "The cells also displayed higher expression levels of CD44 and CD133, representative indicators for cancer stemness." (PMID 28388583, 2017). "Lastly, miR-708-5p suppressed expression of various cancer stem cell markers (CD117, CD34, CD44, octamer-binding transcription factor 4 [OCT4], Aldehyde Dehydrogenase 1 Family Member A2 [ALDH1A2], and NANOG) in A549 and PG cells." (PMID 29050362, 2017). "Quantitative PCR analyses were performed to measure the transcriptional regulation of cancer stemness markers, such as ALDH-1, CD133, CD44, Lgr-5, Msi-1, EphR1, and Bmi-1, by BP compounds." (PMID 28862656, 2017). "CD44 plays an essential role in epithelial mesenchymal transition (EMT), one of the most important events in the cancer invasion process." (PMID 28070170, 2017). "Each BP compound induced the expression of certain cancer stemness markers.1-BP strongly induced the expression of ALDH-1, CD133, Lgr-5, and Msi-1, but had little effect on CD44." (PMID 28862656, 2017). "In turn, EMMPRIN and CD44 can phosphorylate Tyr1068 EGFR, establishing a regulatory loop that fosters cancer cell proliferation and invasion." (PMID 28465354, 2017). "The same phenomenon was also observed in liver (CD24+ and CD133+) and colon (CD44+ and CD26+) cancers." (PMID 28633632, 2017). "Intracellular uptake efficiency was evaluated by Cy5.5–labelled HA‐CE–based nanoparticles in the three cell lines including U87MG (low CD44 expression), MCF‐7 (high CD44 expression) and MCF‐7/ADR (high CD44 expression and showing MDR to anti‐cancer agents)." (PMID 28244656, 2017). "We demonstrated that cancer stem cells reside in perivascular niches and are characterized by high aldehyde dehydrogenase (ALDH) activity and high CD44 expression (ALDHhighCD44high) in HNSCC." (PMID 29245982, 2017). "Furthermore, real-time PCR analysis showed knockdown of lncRNA XIST could markedly decrease the expression of many stemness-associated genes (Nanog, Oct-4 and SOX2) and surface antigens associated with cancer stem cells (CD24, CD44, CD133, CD155 and CD166) (*P<0.05)." (PMID 28837144, 2017). "The HA can specifically bind to specific cell surface receptors like cluster determinant 44 (CD44) or lymphatic vessel endothelial hyaluronan receptor- (LYVE-) 1, which are overexpressed in various cancer cells." (PMID 29097925, 2017). "In this study, we first characterized the well-accepted cancer stem cell surface marker, including CD24, CD44 and CD133 in CSCs isolated by culturing panc-1 cells in serum-free medium." (PMID 28854261, 2017). "Because CSCs exhibit increased aggressiveness, aggressive cancer cells are most commonly identified and sorted by flow cytometry using combinations of CSC cell-surface markers such as CD44, CD133 and EpCAM." (PMID 29156833, 2017). "We observed overexpressed EXT1 in MCF7/ADR cells can facilitate and regulate cancer cell stemness, including increased ALDH+and CD44+/CD24- population, and growth of larger and more numerous mammospheres in MCF7/ADR cells." (PMID 29050299, 2017). "The combination of the transmembrane proteins CD44 and CD24 has been used to characterize the stemness of cancer cells over a long period of time." (PMID 29062075, 2017). "Consistently, the levels of cancer stemness and mesenchymal markers ALDH1 (Aldehyde Dehydrogenase 1), CD44, TAZ, and E2A-E12 were reduced in mammospheres by miR205 (miR), and were recovered by Anti-miR205 (Anti-miR) co-expression." (PMID 29182685, 2017). "Owing to very low percentage of CD44+ and CD90+ cell populations in well-differentiated HCC cells, we isolated cancer stemness sub-populations with the most conservative cancer stemness marker ALDH1 from HepG2 and SNU449 for analysis the expression of 10 RLEs." (PMID 29100421, 2017).
cancer (continued). "Using HCT116 cells as preliminary model to establish if Rimonabant can control cancer stemness, FACS analysis of CD133/CD44 double positive population was performed." (PMID 29354056, 2017). "In non-cancer cell lines including HDF, HMEC, and HEK-293, the overall CD44 expression itself was much lower than that in cancer cell lines, and the level of alternative splice variant isoforms was not significantly higher than that of CD44s." (PMID 28694503, 2017). "Because CD74 and CD44 are both involved in MIF-mediated signalling, CD74 is considered a potential therapeutic target in cancer." (PMID 29190904, 2017). "In light of these considerations, the fact that CD44+/CD24− cells have self-renewal capabilities and have been referred to as ‘cancer stem cells’ is particularly captivating." (PMID 28092266, 2017). "Overexpression of syndecan-1, MUC-1, and the putative cancer stem cell markers CD15, CD24, CD44, and CD133 has been documented on CSF floating cancer cells of BC patients with LM." (PMID 28399903, 2017). "More recently, OC-derived exosomes were reported to transfer CD44 into mesothelial cells, resulting in upregulation of matrix metalloproteinase 9 (MMP9) that, in turn, favoured cancer cell homing and invasion." (PMID 28320418, 2017). "Our results showed that the cancer expression of stem cell markers BMI1, ALDH1 and CD44 were highly upregulated in human SCCHN and mice SCCHN tissues, and NLRP3 inflammasome was closely associated with those makers." (PMID 28865486, 2017). "Particularly, 78% of PDAC patients displayed CTCs expressing, in addition to an epithelial marker (cytokeratin), also a cancer stem cell marker (ALDH, CD133 or CD44)." (PMID 29156578, 2017). "In line with the observed reduction of CD133 and CD44 expression, in HCT116 cells Rimonabant downregulates Lgr5, suggesting a potential role of the compound in the control of cancer stemness." (PMID 29354056, 2017). "According to these findings, it was proposed that an efficient targeting of ESCC cancer stem cells should involve dual targeting of both ICAM-1 and CD44." (PMID 28930282, 2017). "In this pair of comparison, the CD44+ cells had a higher potential of generating in peritoneal cavity of CD44high, CD44+CD24–, CD44+CD24+ cell subpopulations, highlighting the presence of cancer stem cells in a pool of CD44+ cells." (PMID 28622715, 2017). "Although there are various CSC markers, such as CD133, CD44, and ALDH1, displayed on cancer cells, Oct4 expression in these cells plays a major role in anti-apoptosis and maintenance of pluripotency." (PMID 27244887, 2017). "The surface markers of cancer stem cells include CD133, CD44, Oct4, SOX2, Nanog, ALDH1, Bmi-1 and so on25." (PMID 28262804, 2017). "Analysis of carcinoma cells in animals showed bcl‐2, Ki67, VEGFA, CD24 and CD44 expression decrease and Bax, caspase‐3 and ALDH1 expression increase after high‐dose CLO administration." (PMID 28524540, 2017). "In pancreatic cancer, combination of two distinct expression patterns, such as of CD44/CD24 together with the epithelial-specific antigen (ESA) or CD133/CXCR4, can identify the cancer stem-like population." (PMID 27457474, 2016). "Cancer stem cell expression were discovered in plethora of human malignancies; like CD133, CD44 and ALDH1 in solid tumors, CD34 in hematological malignancies." (PMID 27584160, 2016). "Immunohistochemistry double-staining of CD44 and CD24 was also performed on paraffin-embedded primary NPC samples from patients at different stages of the cancer." (PMID 27521216, 2016). "Among the most studied receptor proteins are CD44 and receptor for hyaluronan-mediated motility (RHAMM), as they participate in inflammation and cancer motility, migration and metastasis." (PMID 27999774, 2016). "The spheroids derived from two patients (#6 and #19) expressed activated (stabilized) β-catenin and CSC markers (CD44, CD133 and ALDH1) and maintained the function of CSCs to reconstitute the cancer tissue architecture." (PMID 27562646, 2016).
cancer (continued). "Within cancer cells, CD133 and CD44 were detected in the membrane and cytoplasm, while ALDH1 and Nanog were found only in the cytoplasm." (PMID 27285762, 2016). "Jaggupilli A and Elkord E: Significance of CD44 and CD24 as cancer stem cell markers: an enduring ambiguity.Clin Dev Immunol." (PMID 27454254, 2016). "PTT applied in vitro preferentially targeted the epithelial-like ALDH+ BCSCs, followed by mesenchymal-like CD44+/CD24- BCSCs, compared to bulk cancer cells." (PMID 27679576, 2016). "Using our in vitro model, we found that SOX2 expressing cells displayed several characteristics of cancer stem cells; such as a decreased proliferative rate, a spheroid growth pattern, and increased expression of stem cell markers CD24 and CD44." (PMID 27411517, 2016). "Our meta-analysis suggests that CD44 polymorphisms might not represent risk factors for cancer." (PMID 27738347, 2016). "Previously, we found that the rare CD44+CD54+ cellular subpopulation in rectal and gastric cancer tissues can potentially identify the early progression of cancer." (PMID 27764803, 2016). "Neutralizing antibodies against CD44 and CD166 inhibited the invasiveness of cancer cells in MSS LS513 cells." (PMID 27494849, 2016). "It is a well-established fact that CD44 and CD24 are often co-utilized along with other tertiary markers to isolate TPCs in various cancers." (PMID 27276062, 2016). "Although an enhanced basic level of autophagy was found in the CD44+/CD133+ cancer stem cells, our data suggest that the canonical autophagy in cancer cells plays few roles, if any, in radio-sensitivity." (PMID 27129175, 2016). "Expression of NOTCH1 and its pathway genes maintains cancer stem-like cells (CSCs) in various tumors, as determined by their ability to form spheroids and expression of molecular markers ALDH1, CD133 and CD44." (PMID 27391340, 2016). "A probable reason for this difference is that Fujita and Ikeda used CD44 and CD133 as the marker to identify cancer stem cells, while we used ALDH1." (PMID 28008389, 2016). "The results revealed much more CD44+/CD24-/low positive cells, indicating a high ratio of cancer stem cells in MCF7-ErbB2 cell which was also observed in the ALDH assay." (PMID 27416801, 2016). "CD44 can also positively regulate the expression of Oct4 and p-ERK, both Oct4 and ERK1/2 pathway are vital for regulating pluripotency of cancer stem cells." (PMID 26769843, 2016). "CD44 is a receptor for hyaluronan (HA) that promotes epithelial-to-mesenchymal transition (EMT), induces cancer stem cell (CSC) expansion, and favors metastasis." (PMID 27009862, 2016). "Further investigation of CD44 expression in BSG-null mice and cancer cell lines should be performed to understand the implication of this receptor in lactate transport." (PMID 26099350, 2016). "Several evidences have firmly established the role of CD44 in cell differentiation, epithelial -mesenchymal transition (EMT), invasion and metastatic spread in various human cancers." (PMID 27521214, 2016). "Cancer stem cells are believed to form vascular mimicry channels that express various markers including CD34, CD44, and CD133 as well as PAS+ staining." (PMID 27834402, 2016). "In summary, for the first time, we demonstrated that AQP3 increases CD44 expression through Wnt/GSK-3β/β-catenin signaling pathway and promotes the stem-like properties of cancer cells in GC." (PMID 26918728, 2016). "Inhibitors of CD44 and RHAMM are being tested for cancer treatment with a few inhibitors in clinical trials." (PMID 27595989, 2016). "Future studies will have to address the role of CD44 and RHAMM for radiosensitivity of cancer cells, possibly also including further binding partners of both proteins, such as MET." (PMID 26870892, 2016). "A major receptor for hyaluronic acid, CD44, is an extensively described CSC marker in several human carcinomas." (PMID 27293448, 2016).